IRS2 (insulin receptor substrate 2)
Diseases named in the same sentence as IRS2 in open-access papers (continued):
Sharing a sentence is not in itself a finding about the gene and the disease.
Insulin resistance (continued). "The β cell- and hypothalamus-specific knockout of IRS2 in mice induced obesity and both leptin and insulin resistance." (PMID 30602666, 2018). "ILG appeared to improve insulin resistance by increasing IRS2 and AKT2 mRNA levels in the skeletal muscle." (PMID 30360437, 2018). "First, hepatic IRS-2 expression was found to be downregulated in these animal models, contributing to the development of hepatic insulin resistance." (PMID 29717275, 2018). "Liver IRS-2 protein levels, an indicator of insulin resistance, were lower in HFHS-β-CB1R+/+ compared with SD-β-CB1R+/+ mice." (PMID 29497784, 2018). "Other factors that are related to insulin resistance with Irs-2 deletion in mice can possibly be involved in this basal elevation." (PMID 28539593, 2017). "In this context, Charbonneau and Marette showed that the covalent link of peroxynitrite (ONOO-) to IR, IRS-1, IRS-2 and Akt is also involved with insulin resistance after lipid infusion." (PMID 28835706, 2017). "More importantly, we provided evidence that SIRT1 knockdown led to cardiac insulin resistance, as low expression of SIRT1 caused reduced IRS2 expression and impaired insulin signaling in both in vivo and in vitro models." (PMID 28883902, 2017). "Long-term overnutrition leads to a chronic low-grade inflammation, which promotes insulin resistance, for instance via insulin receptor substrate 2 (IRS2) downregulation in SAT and thus precedes type 2 diabetes mellitus (T2DM) and other metabolic disorders." (PMID 27900559, 2017). "The transcription factor Srebf1 (SREBP1) is a key regulator of lipogenic enzyme expression in the liver and mediates hepatic insulin resistance through inhibition of IRS-2." (PMID 28351387, 2017). "Why the expression of IRS2 in the kidney cortex is preserved in insulin resistance is not completely understood." (PMID 27247938, 2016). "Data from mice showing that increasing IRS2 levels provides relief in terms of hepatic insulin resistance are very encouraging." (PMID 27514532, 2016). "Improvement of insulin resistance would be expected to ameliorate hyperinsulinemia, restore Irs2 expression and thereby improve the blood glucose levels." (PMID 27708333, 2016). "In insulin resistance, the signaling cascade via IRS2 seems to be impaired while the signaling cascade via IRS1 seems relatively intact." (PMID 27247938, 2016). "Taken together, two factors seem to be important in the pathogenesis of ‘selective insulin resistance' in the liver: both reduced Irs2 expression and intact Irs1 expression." (PMID 27708333, 2016). "Irs1 and Irs2, as also Akt2 are essential for the development of steatosis in the presence of insulin resistance." (PMID 27708333, 2016). "For example, in adipose tissue, both IRS1-dependent and IRS2-dependent signals are impaired in insulin resistance." (PMID 27247938, 2016). "On the basis of these findings, we propose that ‘selective insulin resistance' is produced as a result of predominant and intact expression of Irs1 in the PV zone, and downregulation of Irs2 expression in both the zones in the presence of hyperinsulinemia." (PMID 27708333, 2016). "Previously, homozygous disruption of IRS1 transcription led to mild insulin resistance, while IRS2-knockout mice exhibited severe insulin resistance." (PMID 26257839, 2015). "Enhancing insulin resistance of nonalcoholic fatty liver disease by increasing the expression of IRS-2." (PMID 26633388, 2015). "Homozygous interruption of IRS1 expression in mice led to mild insulin resistance, while complete depletion of IRS2 expression in rodents resulted in severe insulin resistance." (PMID 26693205, 2015). "Insulin resistance is known showing a reduced insulin sensitivity of peripheral tissue with aberrant IRS-2 and downstream members of the insulin signaling pathway." (PMID 26504484, 2015).
Insulin resistance (continued). "Insulin resistance is thus associated with reduced responses to insulin signaling in the IR/IRS-1/PI3K and greatly with IGF1 in the IGF1R/IRS-2/PI3K signaling pathways." (PMID 25346723, 2014). "By contrast, the reduction of IRS2 expression seems to be a key factor in several forms of insulin resistance in liver." (PMID 24982885, 2014). "Consistent with this view, a recent study showed that the expression of IRS2 as well as insulin-mediated Akt phosphorylation in renal tubules is preserved in Zucker fatty rats that show marked insulin resistance due to defective leptin signaling." (PMID 24982885, 2014). "In particular, the mRNA down-regulation of Insr, Irs1 and Irs2, in association with reduced phosphorylation of Akt and reduced Glut4 expression, suggests that Zip7 activity may be amenable to manipulation as a novel approach for the treatment of insulin resistance in skeletal muscle." (PMID 24265765, 2013). "Reduced expression of IRS-2 has been described in a number of “in vivo” models of insulin resistance." (PMID 23560040, 2013). "Accordingly, a link between GK and IRS-2 is required for compensatory β-cell hyperplasia in response to insulin resistance induced by a high-fat diet." (PMID 23560040, 2013). "Deletion of Irs-2 in mice is known to generate insulin resistance which is particularly pronounced in liver." (PMID 23560040, 2013). "For example, IRS1 gene knockout mice have mild insulin resistance with normoglycemia, while IRS2 gene knockout mice suffer from severe hyperglycemia with insulin resistance and reduction of the β cell mass." (PMID 23346100, 2012). "Like the IRS2 null mice with severe insulin resistance, glucose and FFA treatment of insulinoma cells and primary islets induces a state of insulin resistance." (PMID 21541314, 2011). "IRS2 knockout mice develop insulin resistance, decreased beta-cell proliferation, overt diabetes, and female sterility." (PMID 21754917, 2011). "Hepatic insulin resistance is caused by alterations in substrate 1 (IRS-1) and substrate 2 (IRS-2) of the insulin receptor." (PMID 20946638, 2010). "Fasting is reported to enhance insulin-induced IRS-1 and IRS-2 tyrosine phosphorylation and association with PI3-kinase in liver and muscle of animal models of insulin resistance (streptozotocin treated rats)." (PMID 18570670, 2008). "A study involving Korean women found that PAHs may contribute to the pathogenesis of insulin resistance through methylation mediated inhibition of the IRS2 gene." (PMID 40567989, 2025). "The results indicate that IRS1 or IRS2 may facilitate insulin action in the liver, thereby maintaining systemic glucose tolerance, particularly when β-cell function is able to offset insulin resistance." (PMID 40747301, 2025). "Preventing insulin resistance and enhancing IRS2 function may be effective strategies to prevent or treat insulin resistance." (PMID 40747301, 2025). "In summary, excessive hepatic glucose and fructose metabolism also drives insulin resistance through glycolytic overload-linked pathways: hexosamine pathway—stabilizing GCK and ChREBP to proteolysis, the latter suppressing expression of IRS-2; and increased MG with activation of the UPR." (PMID 41196673, 2025). "Several animal studies reported that long-term caffeine intake is inversely associated with insulin resistance through various mechanisms, including improved insulin/IGF-1 signaling via the induction of insulin receptor substrate 2 or a decrease in circulating catecholamines." (PMID 40362793, 2025). "Notably, irisin has been shown to enhance PI3K/AKT insulin signaling and reduce the serine phosphorylation of IRS-1 and IRS-2, which are key molecular mechanisms contributing to insulin resistance." (PMID 39769243, 2024). "This early decrease in miRNA-431-5p may be a protective mechanism to increase insulin receptor substrate 2 abundance in the setting of insulin resistance in youth-onset type 2 diabetes." (PMID 38815053, 2024).
Insulin resistance (continued). "Furthermore, in response to intracellular and extracellular stresses, the activations of JNK and NF-κB induce insulin resistance through the serine phosphorylation of the insulin receptor substrate (IRS)-1 or IRS-2, subsequently blocking insulin signaling." (PMID 38248467, 2024). "The two protein molecules interacted with the insulin receptor, and their overexpression negatively regulated an insulin-induced phosphorylation of insulin receptor substrates (IRS, gene name: Irs1 and Irs2), which is one of the most important factors contributing to insulin resistance in the body." (PMID 39063287, 2024). "Similarly, the expression of c-miR-126 has also been shown to be altered with exercise and concomitantly a potential biomarker for type-2 diabetes due to its interference with insulin signaling by targeting IRS1 and IRS2, resulting in insulin resistance." (PMID 38903909, 2024). "Lipid intermediates, such as diacylglycerols, could inhibit insulin signaling pathways by impairing insulin receptor substrate 2 (IRS2) phosphorylation as well as elevating the PKC pathway in the liver resulting in insulin resistance." (PMID 39021593, 2024). "Modulating insulin signaling pathways through agents that enhance IRS-1 and IRS-2 function or inhibit their aberrant phosphorylation could improve glucose uptake and reduce insulin resistance." (PMID 39519193, 2024). "Moreover, reducing IRS2 expression in the liver of WT mice worsened Dex-induced insulin resistance and further diminished Dex-suppressed hepatic AKT activity." (PMID 37253782, 2023). "Recent studies have shown that SREBP-1c can also inhibit the transcription of insulin receptor substrate-2 (IRS-2), thereby exacerbating insulin resistance; this suggested that it might have a negative regulatory effect on insulin signaling." (PMID 37299470, 2023). "Insulin resistance in Irs2–/–;Cdk4-R24C/R24C mice likely contributed to increased proliferation." (PMID 37712417, 2023). "Additionally, high cholesterol and cholate diets induced hepatic insulin resistance in mice via inhibition of insulin receptor substrate-2 (IRS-2) expression." (PMID 37073330, 2023). "He thought the failure that beta-cell mass failed to compensate for insulin resistance was caused by a significant increase in beta-cell apoptosis, and highlighted the role of IRS-2 signaling in beta-cell survival." (PMID 36743933, 2022). "The treatment of PPH was also found to regulate the insulin signaling in our study, which is consistent with a previous study reporting that the intragastric administration of PPH upregulated the gene expressions of IRS1 and IRS2 in the liver of diabetic mice, and reduced insulin resistance." (PMID 36011893, 2022). "As for other parameters, we observed that the Z-Lg group showed improved insulin resistance and leptin resistance, which was achieved by increases in the protein levels of components of the IRS2-AKT-FOXO1 pathway and JAK2-SOCS3-STAT3 pathway in the hippocampus and cortex." (PMID 35721013, 2022). "In conclusion, exenatide may improve hepatic insulin resistance (IR) by inhibiting adipokines and regulating the expression of key proteins in the IRS2/PI3K/Akt2 pathway." (PMID 36246878, 2022). "Knockdown of Jund, Max and Mxi1 downregulated Irs2, which suggested that these transcription factors are involved in Irs2 transcription and may contribute to insulin resistance." (PMID 34921686, 2022). "Finally, TMAO induction of insulin resistance was more directly measured by reduced expression of the insulin signaling cascade including insulin receptor substrate 2 (IRS2), PI3K, RAC-β serine/threonine-protein kinase (AKT) and glucose transporter 2 (GLUT2)." (PMID 34445033, 2021). "However, phosphorylation of IRS-2 and IRSs (IRS-I and IRS-2) association with PI3K was significantly reduced in muscle of transgenic mice causing whole-body insulin resistance." (PMID 34071721, 2021).
Insulin resistance (continued). "The insulin-dependent IRS2-AKT signaling pathway is the main pathway of insulin resistance." (PMID 34485269, 2021). "IRS1 and IRS2 are important for the development of NAFLD in the presence of insulin resistance." (PMID 34449768, 2021). "The hallmark of insulin resistance in PI3K pathway is the inhibition of the insulin receptors and/or its substrates, especially the insulin receptor substrate 2 (IRS-2) and IRS-1, leading to hyperinsulinemia and hyperglycemia in the peripheral tissues, such as in muscle and adipose tissues." (PMID 33672171, 2021). "Brain insulin resistance is shown to a disturbance of brain insulin signaling in experimental animals, which is represented by the attenuation of insulin receptor substrate-2 (IRS2) → phosphoinositide 3-kinase → phosphorylated Akt → phosphorylated glycogen synthase kinase-3β (GSK-3β)." (PMID 33494481, 2021). "Therefore, the effect of lncARSR/YAP1/IRS2/AKT axis on NAFLD by regulating insulin resistance needs further elaboration." (PMID 32169080, 2020). "IRS2 is one of the most important molecular switches mediating hepatic insulin receptor signalling and is involved in the phenomenon of selective insulin resistance, in which the lipogenic actions of insulin remain intact while glucose uptake and glycogen synthesis are disrupted." (PMID 32710190, 2020). "Dysfunction of IRS-1 and IRS-2 would lead to insulin resistance and NAFLD." (PMID 31805951, 2019). "Risk alleles like FTO, ADIPOQ, INSR, IRS1, IRS2, PPARG, CAPN10 may leave individuals more vulnerable to insulin resistance and/or adiposity (which can result in peripheral insulin resistance), leading to high circulating insulin." (PMID 31367382, 2019). "The adverse effect of diet overloading on the development of insulin resistance was cumulative and not cancelled by IRS-2 deficiency." (PMID 30975165, 2019). "Mice with global deletion of Irs2 develop progressive diabetes due to a combination of systemic insulin resistance, hypothalamic obesity and pancreatic beta cell failure which together have precluded detailed analysis of the specific role of macrophage IRS2 signaling in physiology." (PMID 30553769, 2019). "Murine experiments reveal that targeted depletion of IRS-1 or IRS-2 leads to insulin resistance." (PMID 31920981, 2019). "Additionally, genetic alterations in these genes are strongly involved, especially mutations in five genes (DGAT1, FASN, LPL, IRS2, and YWHAZ), in lipid synthesis, insulin resistance, and cancer progression." (PMID 31717414, 2019). "Furthermore, ILG improves insulin resistance by suppressing gluconeogenesis and increasing mRNA IRS2 expression and suppresses inflammatory cytokine levels." (PMID 30360437, 2018). "Taken together with the finding that ALT, which was already elevated in the SS group, is the parameter most strongly associated with IRS-2/PEPCK/G6Pase expressions, selective insulin resistance associated with IRS-2 downregulation is likely to occur in the early stages of NAFLD." (PMID 29717275, 2018). "Thus, our integrated analyses of multiple gene expressions suggest that decreased IRS-2 plays an important role in the development of hepatic insulin resistance in humans with NAFLD." (PMID 29717275, 2018). "These analyses revealed that selective insulin resistance occurs in the human liver, and that differential expression patterns of IRS-1 and IRS-2 may contribute to the underlying mechanism." (PMID 29717275, 2018). "Hepatic IRS-1 and IRS-2 play a pivotal role in mediating insulin-dependent regulation of glucose and lipid metabolism; dysregulation of abundance and/or phosphorylation status of IRS-1 and IRS-2 in the liver are significant factors in the pathogenesis of insulin resistance and type 2 diabetes." (PMID 30225267, 2018).
Insulin resistance (continued). "Ubiquitin D (UBD) expression is upregulated in the pathogenesis of diabetes, and UBD inhibits the activity of insulin receptor substrates 1 and 2 (IRS1 and IRS2), diminishing their ability to accept insulin, which leads to the downregulation of PI3KR1 expression and causes insulin resistance." (PMID 30131712, 2018). "Factors that interfere with either expression or phosphorylation of IRS1 and IRS2 may contribute to insulin resistance." (PMID 30602666, 2018). "The dual knockdown of IRS-1 and IRS-2 resulted in systemic insulin resistance and hepatosteatosis." (PMID 26866272, 2016). "Hepatic insulin resistance is also associated with reduced expression of IRS-1 and IRS-2." (PMID 26866272, 2016). "The difference between the role of IRS1 and IRS2 in insulin signaling cascade could account for the existence of selective insulin resistance in liver." (PMID 27247938, 2016). "Deepure tea intragastrically given for 14 days could reverse the downregulation of IRS-2 protein in dietary-induced obese mice, which may be contributable to the improvement of hepatic insulin resistance." (PMID 26504484, 2015). "In insulin resistance, the IRS2 in kidney cortex is exceptionally preserved and may mediate the stimulatory effect of insulin on NBCe1 to cause hypertension in diabetes via sodium retention." (PMID 26491696, 2015). "In insulin resistance, the IRS2 in kidney cortex is exceptionally preserved and may mediate the stimulatory effect of insulin on NBCe1." (PMID 26491696, 2015). "A G1057D polymorphism in IRS2 is associated with diabetes risk in Han Chinese, but not with insulin resistance or secretion in a Finnish population." (PMID 25774510, 2015). "Future studies are required to determine whether the IRS2-dependent stimulatory insulin signaling in PTs is preserved in common forms of insulin resistance." (PMID 24982885, 2014). "Either IRS-1 or IRS-2 gene deletion in mice leads to insulin resistance." (PMID 25580119, 2014). "Interestingly, the impairment of GK activity was rescued in the RIP-Irs-2/IRS-2(−/−) model where restored IRS-2 function in pancreatic beta cells provides long-term compensation for peripheral insulin resistance." (PMID 23560040, 2013). "The reduced GK activity in IRS-2(−/−) mice may be due to insulin resistance in these animals since this impairment was overcome by introduction of the RIP-Irs-2 transgene to restore β-cell compensation." (PMID 23560040, 2013). "IL1-β and TNFα induce IRS-2 phosphorylation, which leads to insulin resistance, followed by the apoptotic death of β cells; the inhibition of cytokines by AS101 may contribute to β cell preservation." (PMID 22761194, 2012). "The evidence of the interaction between 14-3-3 proteins and the signal transducer IRS-2 in vivo opens several novel perspectives in the (patho)physiological regulation of the biological function of IRS-2 including its role in metabolic disorders such as insulin resistance and type 2 diabetes." (PMID 22912850, 2012). "Over expression of TNF causes insulin resistance through the inhibition of PI3K-mediated activation of insulin receptor substrate 1 (IRS-1) and insulin receptor substrate 2 (IRS-2), and tyrosine phosphorylation of the mitogen-activated protein kinases p42MAPK and p44MAPK." (PMID 22451839, 2012). "The systemic and tissue pro-inflammatory profile in the A2bAR KO could contribute to the observed downregulated IRS-2, and impaired Akt signaling, and to the peripheral tissue insulin resistance." (PMID 22848385, 2012). "However, we find that disrupting Irs2 in Tg2576 mice results in improvement of both Aβ plaque burden and behaviour despite an exacerbation of tau phosphorylation and the presence of insulin resistance." (PMID 19523444, 2009). "Therefore, our finding of lower hepatic IRS2 could contribute to insulin resistance in LBW newborn goats, as evidenced by the in vivo studies." (PMID 38596462, 2024).